STAT3 (signal transducer and activator of transcription 3)
Diseases named in the same sentence as STAT3 in open-access papers (continued):
Sharing a sentence is not in itself a finding about the gene and the disease.
cancer (continued). "Compared to current HCC therapies that offer only minimal improvements in overall survival, niclosamide offers promise as a cancer multitool compound due to its ability to decrease the AR/AR-SV protein and prevent rebound oncogenic signaling through its activity against NF-κB, STAT3, and KRAS." (PMID 40805231, 2025). "STAT3 may induce genes that suppress cancer progression, such as FOXO1, p14ARF, and CDKN1A (P21), as previously reported." (PMID 41104968, 2025). "we speculate that FHOD1 could trigger a series of downstream events by activating the STAT3 signaling pathway, which in turn promotes cancer cell invasion and metastasis." (PMID 40364836, 2025). "STAT3 plays a crucial role in the development of various cancer cells." (PMID 40118821, 2025). "Therefore, the pursuit of highly specific and potent compounds targeting STAT3 activity remains a critical goal for potential cancer prevention and therapy." (PMID 40723906, 2025). "In all, STAT3 has been shown to be an appealing pan-cancer therapeutic target." (PMID 40075607, 2025). "Importantly, IL-22 was found to enhance PC stemness through IL-22RA1/STAT3 signaling, elucidating the role of microenvironmental factors in regulating cancer stemness." (PMID 40806452, 2025). "Additionally, mTORC1 directly phosphorylates STAT3 at Ser 727, driving cancer cell proliferation and the formation of large cancer cell clusters." (PMID 40407951, 2025). "However, in cancer cells, hyperphosphorylated STAT3 activates oncogenic transcription factors such c-Myc, Cyclin-D1, Bcl-xL, VEGF, and Oct-4, leading to enhanced cell proliferation and survival, as well as aggressive cancer cell stemness." (PMID 40075607, 2025). "More importantly, EGR146–49, LCN250 and SOCS351 could be upregulated by IL-1α, IL-1β and IL-6 in immune or cancer cells by activating the NF-κB or STAT3 signaling pathway." (PMID 40523992, 2025). "In line, WFDC21P has been reported to impact glycolysis and STAT3 signaling in cancer." (PMID 41424764, 2025). "Accordingly, STAT3 has emerged as a potentially valuable target for cancer treatment." (PMID 40242440, 2025). "RPPA analysis further indicated that macrophage-derived exosomes induced changes in the expression levels of several proteins associated with aggressive characteristics in cancer cells, including MAPK (ERK), vimentin, AMPKa, eIF4G, STAT3, and B-Raf in PANC-1 cells." (PMID 40624025, 2025). "Thus, any inhibitor of nuclear STAT3 risks targeting healthy cells in addition to cancer cells and inhibiting cell growth and proliferation." (PMID 40075607, 2025). "Our results suggest that post-translational modifications of STAT3, particularly acetylation, play a critical role in maintaining the stemness of cancer cells, which could make it a potential target for therapeutic intervention." (PMID 40083697, 2025). "STAT3 is now recognized as a significant participant in the development of human cancer." (PMID 40217305, 2025). "Another study developed a multi-epitope vaccine targeting important cancer antigens like STAT3, HER2, and GRB7 using a multimodal strategy that included MHC I, MHC II, CTL, and B-cell epitopes created from MAGE-A3, EGF, and MUC-1 by in silico immunoinformatics techniques." (PMID 40453095, 2025). "Targeting Y705 alone may reduce STAT3’s nuclear transcriptional activity, while inhibiting S727 phosphorylation could impair the mitochondrial functions critical for cancer cell metabolism." (PMID 40075607, 2025). "Furthermore, the combined effects of DZN and PNR markedly reduced cancer cell migration and STAT3 phosphorylation." (PMID 40217305, 2025). "Moreover, alternative routes such as cytokine and growth factor receptors, oncogenic kinases (e.g., SRC, BCR-ABL), or non-canonical pathways involving mitochondrial STAT3 and unphosphorylated STAT3 can allow cancer cells to bypass upstream inhibition." (PMID 40723906, 2025). "KDM1A and STAT3 were significantly higher in cancer cells than in normal cells." (PMID 40246812, 2025).
cancer (continued). "Notably, CCT4 has been linked to the stabilization of oncogenic signaling proteins, for instance, inhibiting CCT4/TRiC can impede STAT3 maturation in cancer cells." (PMID 41403933, 2025). "Further, STAT3 regulates various other aspects of cancer cells, including migration and metastasis." (PMID 40176890, 2025). "Therefore, targeting STAT3 can enhance the anti-cancer immune response of tumors, rescue the suppressed TIME, and simultaneously target the connection between STAT3-CXCL5 to reduce neutrophil infiltration and effectively inhibit squamous transformation." (PMID 40568576, 2025). "Additionally, CD44 can bind nuclear STAT3 and p300 acetyltransferase, promoting STAT3 acetylation, which enhances cell proliferation and cancer stem cell like properties in colon and other cancer cells." (PMID 40438109, 2025). "Additionally, CAF-derived IL-6 activates the JAK2/STAT3 pathway in cancer cells, inducing EMT and enhancing metastatic potential, thereby reinforcing a positive feedback loop that sustains IL-6 expression." (PMID 40718440, 2025). "AKT serine–threonine kinase (AKT), extracellular signal-regulated kinase (ERK), and signal transducer and activator of transcription 3 (STAT3) are critical pathways involved in cancer cell proliferation and metastasis, playing essential roles in EC progression." (PMID 39558814, 2025). "Inhibiting the JAK/STAT3 pathway in murine models significantly attenuates lipolysis and prevents adipose tissue wasting, highlighting the therapeutic potential of STAT3 blockade in cancer cachexia." (PMID 40704145, 2025). "The JAK and STAT proteins, especially STAT3, are promising targets for cancer therapy." (PMID 40841364, 2025). "By controlling metabolism, the STAT3 pathway can also affect cancer cell sensitivity to drugs." (PMID 40052129, 2025). "CAV1 inhibition reduced expression of dormancy regulators E-cadherin, RAC1 and p21, enhanced cancer stemness markers, and disrupted downstream STAT3/P70S6K and AMPKα signalling pathways, prompting cancer cells to exit from dormancy and initiate autophagy-induced cell death." (PMID 40715090, 2025). "Activated STAT3 is involved in the expression of numerous genes that are crucial for cancer progression, including those involved in migration and invasion (Matrix Metalloproteinase 2 (MMP2), MMP9), epithelial–mesenchymal transition (EMT) properties, and preventing escape and attack." (PMID 40427146, 2025). "Similarly, TWP-mediated inhibition of STAT3 phosphorylation dismantles a key driver of immune evasion, metastasis, and cancer stemness." (PMID 41181611, 2025). "Additionally, understanding the complex molecular interactions within the PTK2B/STAT3/GPX4 pathway is crucial for optimizing ferroptosis-based cancer therapies." (PMID 41166024, 2025). "Therefore, promoting STAT3 degradation can suppress c-Myc transcription and reduce cancer cell activity." (PMID 40118821, 2025). "In addition to STING, it was previously shown that STAT3 also modulates autophagy in different cancer types through transcriptional regulation of autophagic-related genes and/or interaction with autophagic-related proteins." (PMID 40743845, 2025). "Together, these findings highlight STAT3’s critical role in muscle wasting by integrating mitochondrial dysfunction, protein degradation, and metabolic disturbances, thereby reinforcing its potential as a therapeutic target for mitigating cancer cachexia." (PMID 40704145, 2025). "Furthermore, constitutive STAT3 activation drives immunosuppression, thus allowing cancer evasion from cytotoxic T-lymphocytes." (PMID 41463071, 2025). "Various molecular approaches have been developed to inhibit STAT3 signaling in cancer." (PMID 41031165, 2025).
cancer (continued). "Taken together, these results confirm that STAT3 signaling is highly activated in protumoral neutrophils and might play a role in cancer progression." (PMID 40885734, 2025). "Moreover, SAM's influence on cancer-related pathways can have downstream effects on the cell cycle and apoptosis, potentially leading to a reduction in the expression of the STAT3 protein." (PMID 40019515, 2025). "Although better understanding of MDSC biology is needed to open new windows of therapeutic opportunities, given that the STAT3 signaling pathway is a central regulator in tumorigenesis and the generation of M-MDSCs, there is huge potential in new cancer chemotherapies targeting the STAT3 pathway." (PMID 40805183, 2025). "These inflammatory responses activate transcription factors that are extensively involved in cancer development and progression, such as signal transducer and activator of transcription 3 (STAT3), hypoxia-inducible factor 1 alpha (HIF1α), and nuclear factor-κB (NF-kB)." (PMID 40806452, 2025). "Interleukin-6 (IL-6) family cytokines activate the JAK/STAT3 pathway via the IL-6Rα/gp130 receptor complex, thereby inducing acute-phase protein synthesis, skeletal muscle proteolysis, and browning of adipose tissue—core phenotypic features of cancer cachexia." (PMID 41002589, 2025). "However, in cancer cells, there is an abnormal dysregulation of STAT3 activation due to increased STAT3 gene expression." (PMID 39898127, 2025). "STAT3 is active in multiple forms of cancer, lung cancer included, making it a suitable target." (PMID 39926108, 2025). "M2 macrophages facilitate cancer cell migration in HCC through the TLR4/STAT3 signaling pathway." (PMID 40136652, 2025). "Therefore, IL-6 inhibitors are being studied for their potential application as key molecules in cancer therapy that target the IL-6/JAK2/STAT3 signaling pathway." (PMID 40725854, 2025). "Importantly, we discovered that p-STAT3 in cancer cells formed cytoplasmic and nuclear biomolecular condensates which rapidly disassembled in cells exposed to hypotonic conditions, and reassembled when cells were shifted to isotonicity." (PMID 40643468, 2025). "By inhibiting STAT3 through the circKIF4A‐miR‐637 axis, it may be possible to resensitize cancer cells to existing therapies, such as chemotherapy, targeted therapy, and immunotherapy." (PMID 40860906, 2025). "The known benefit of activating STAT‐3 is that it can slow down the development of cancer." (PMID 40842665, 2025). "Collectively, these findings underscore STAT3’s multifaceted role in mediating adipose tissue atrophy in cancer cachexia through its regulation of lipolytic enzymes, suppression of lipogenesis, impairment of mitochondrial function, and modulation of key metabolic pathways." (PMID 40704145, 2025). "While significant progress has been made with respect to STAT3 inhibitors for cancer applications, more mechanistic data are needed on the role of STAT3 in cancer in order to improve the translation of pre-clinical STAT3 inhibitors to clinically meaningful therapeutics." (PMID 40075607, 2025). "In cancer, STAT3 is important for the T-cell suppression exerted by MDSCs." (PMID 38720891, 2024). "However, in aggregate, STAT3 activation in immune cells helps create an immunosuppressive microenvironment that is permissive to the maintenance and spread of cancer cells." (PMID 38611065, 2024). "A recent review thoroughly examined the functions of STAT3 in cancer and CSCs." (PMID 39204369, 2024). "Notably, cancer cell lysis obtained with these NPs resulted in up to 45% reduction in tumor volume in vivo, accompanied by significant suppression of STAT3 protein expression both in vitro and in vivo." (PMID 39065565, 2024).
cancer (continued). "Therefore, inhibiting STAT3 signaling by compounds was one of the favorite strategies to develop new cancer treatments." (PMID 38342622, 2024). "In addition, STAT3 has also been identified as a regulator of CDKN1A transcription in various cancer cells." (PMID 38553760, 2024). "Furthermore, evidence suggests that the activation of STAT3 is associated with the EMT process and cancer progression." (PMID 39770571, 2024). "Since STAT3 is a potent oncogene in various types of cancer, the PKA-DARPP32-STAT3 axis may contribute to tumorigenesis at sites other than the stomach." (PMID 38233872, 2024). "Immunofluorescence revealed reduced p-STAT3 expression in ALKBH5-knockdown cancer cells." (PMID 38872221, 2024). "To assess the clinical relevance of our hypothesis, we analyzed RNA sequencing data across some epithelial cancers from TCGA and found that STAT3 is overexpressed and correlates with poor overall survival in these cancer types." (PMID 38326371, 2024). "Our findings present USP21 DUB as a positive controller of STAT3 activity and cancer metabolism." (PMID 39305962, 2024). "Likewise, TAMs conditioned by CRC notably elevate IL-6 secretion, activating the Jak2/STAT3 pathway and indirectly boosting forkhead box Q1 (FoxQ1) expression in cancer, thus reinforcing EMT and cancer stem cell attributes." (PMID 39286635, 2024). "The short-term MTT assay and the long-term colony formation experiment revealed that andrographolide significantly increased doxorubicin-induced cell death in cancer cells, showing that andrographolide increases cancer cell sensitivity to doxorubicin primarily through STAT3 inhibition." (PMID 38397437, 2024). "Thus, the data are in line with previous findings that MUC1 CT enhances STAT3 activation in cancer cells." (PMID 38326371, 2024). "As reported, hyperactivation of STAT3 commonly exists in almost all cancer types." (PMID 38245798, 2024). "Signal transducer and activator of transcription 3 (STAT3) is a protein that regulates cell proliferation and differentiation, and it is attracting attention as a new index for evaluating cancer pathophysiology, as its activation has been highly correlated with the development and growth of tumors." (PMID 38834900, 2024). "Furthermore, specific targeted intervention of the related proteins in the crosstalk signal axis of CXCL12/STAT3 can pave new avenues for cancer treatment." (PMID 38920657, 2024). "The IL-6 binds to IL-6R on the receptor of cancer cells to induce STAT3 axis." (PMID 39014491, 2024). "Among them, STAT3 and NFkB are involved in the classical pathway linking inflammation and cancer." (PMID 39872979, 2024). "M2 polarization is dependent on STAT3 signaling which is often directly elicited by cancer cells." (PMID 39200368, 2024). "The JAK2/STAT3 hyperactivity results in the onset and development of cancer." (PMID 38706884, 2024). "STAT3 is persistently activated in many types of human cancers including TNBC." (PMID 38532948, 2024). "VEGF upregulation is mediated by excess STAT3 signaling in diverse human cancer cell lines." (PMID 38245798, 2024). "Furthermore, significant reduction in mRNA and protein levels of PD-L1 and STAT3 molecules was observed in B16-F10 and 4T1 cancer cells." (PMID 39065565, 2024). "Additionally, STAT3, which plays a critical role in cancer progression by regulating the genes involved in cell growth, survival, and metastasis, was significantly suppressed in the K-OVV group compared to the control and OVV groups." (PMID 39519023, 2024). "STAT3 orchestrates oncogenic pathways, crucial in tumorigenesis and cancer stemness." (PMID 39309691, 2024). "Cancer cell-specific-targeting of JAK2/STAT3 or combinations with immunotherapy may be required for further evaluation of JAK2/STAT3 signaling as a cancer therapeutic target." (PMID 38297352, 2024).
cancer (continued). "Consequently, clinical trials testing the anti-cancer effects of atovaquone are currently in progress for STAT3-driven cancers, including ovarian cancer (ClinicalTrials.gov NCT05998135) and AML (ClinicalTrials.gov NCT03568994)." (PMID 38611065, 2024). "Meanwhile, cross-sectional profiling of cancer focusing on the expression and function of STAT3 will provide significant information on the characteristics, immunological status, and metastatic potential of cancers, helping to assess the effectiveness of STAT3 inhibitors for cancer treatment." (PMID 38834900, 2024). "Furthermore, CSC-Exos expressing IL-6, p-STAT3, TGF-β1, and β-catenin promote the generation of cancer-associated fibroblasts and M2 macrophages in colon cancer." (PMID 39200273, 2024). "Many types of cancer have shown that STAT3 can mediate resistance to chemoradioimmunotherapy, and targeting STAT3 may overcome radioresistance." (PMID 40191738, 2024). "It was found that the core targets such as PTGS2, CXCL8, TGFB1, and STAT3 were mainly enriched in the pathways related to cancer and several inflammatory factors, and that tretinoin and PTGS2 as well as tretinoin and PTGS2, CXCL8, and STAT3 had strong binding activities." (PMID 39224778, 2024). "The role of STAT3 in oncogenesis and cancer progression has garnered substantial attention." (PMID 39309860, 2024). "This suggests that targeting STAT3 degradation could be an effective strategy for combating cancers driven by aberrant STAT3 activity." (PMID 38773495, 2024). "The CD44/STAT3 axis is involved in cancer progression and therapy resistance." (PMID 39766086, 2024). "Since STAT3 is a key driver of embryonic stem cell (ES) and CSC self-renewal, here, we investigate whether p27pTpT can drive stem or progenitor cell expansion in development and in different cancer models through transcriptional coregulation of STAT3." (PMID 38886396, 2024). "To identify possible protein targets, we carried out Autodock vina molecular docking calculations of 2a (the phenolic precursor of the salt 3a) and niclosamide bound to the protein structures of STAT3 and β-catenin, both of which are known niclosamide targets in cancer cells." (PMID 39062194, 2024). "ROS regulate several cell signaling pathways involved in cellular transformation, inflammation, angiogenesis, and cancer, primarily through protein pathways such as transcription factors NF-κB and STAT3, hypoxia-inducible factor-1α, kinases, growth factors, cytokines, and others." (PMID 39273267, 2024). "Furthermore, STAT3 signaling is now well established as a primary intrinsic route driving cancer apoptosis, inflammation, cellular transformation, angiogenesis, and metastasis." (PMID 38195397, 2024). "Additionally, STAT3 is involved in reprogramming cancer cell metabolism, affecting pathways such as aerobic glycolysis, oxidative phosphorylation, and mitochondrial function." (PMID 39597836, 2024). "Besides its important role in regulating proliferation, survival and differentiation of cancer cells, STAT3 has a complex regulatory function in their immune evasion from NK-cell surveillance." (PMID 39034990, 2024). "Therefore, a comprehensive investigation into the functional mechanisms and regulatory pathways of the JAK/STAT3 axis holds significant importance for cancer treatment and prevention." (PMID 39108268, 2024). "YY002induction of mitochondrial STAT3 dysfunction as well as suppressionof cancer cell OXPHOS suggested that cancer cells may be more sensitiveto the cytotoxic effects of YY002 under conditions of increased dependenceon mitochondrial activity." (PMID 38559310, 2024). "Previous studies have confirmed that MET is a significant driver of mutation in NSCLC, activating signaling pathways downstream of PI3K/AKT, Ras-MAPK, and STAT3 (signal transducer and activator of transcription 3), which promote cancer proliferation, migration, and invasion." (PMID 39201787, 2024).